APOLD1 (apolipoprotein L domain containing 1)
Description:
Is a modulator of endothelial barrier permeability, required for proper organization of endothelial cell-cell junctions and cytoskeleton. It also plays a role in the modulation of secretory autophagy. May affect blood-brain barrier permeability.
Synonyms: VERGE; FLJ25138; DKFZP434F0318; BDVAS
Tractability: Antibody: UniProt places it where antibodies can reach, with high confidence; UniProt predicts a signal peptide or a membrane-spanning region; its Gene Ontology location is reachable by antibodies, with medium confidence; the Human Protein Atlas places it where antibodies can reach. PROTAC: ubiquitination databases record sites on it.
Gene: Protein-coding gene on chromosome 12 (12,725,917 to 12,829,975, forward strand). Ensembl gene ENSG00000178878.
Subcellular location: Cell membrane; Cell junction; Cytoplasmic vesicle, secretory vesicle
Subcellular location (Human Protein Atlas): Nucleoplasm; Plasma membrane
Gene Ontology:
Molecular function: lipid binding
Biological process: autophagosome-dependent secretion; regulation of membrane permeability; angiogenesis; regulation of endothelial cell differentiation; lipid transport; lipoprotein metabolic process
Cellular component: anchoring junction; cell-cell junction; nucleoplasm; plasma membrane; Weibel-Palade body; membrane; extracellular region; transport vesicle
Genetic constraint (gnomAD): Loss-of-function variants: 24 observed, 13.85 expected, observed/expected ratio (o/e) 1.73, 90% interval 1.21 to 1.96. The synonymous counts are far from expectation, so gnomAD's model fits this gene poorly and the ratio says little. Missense variants: 394 observed, 286.85 expected, observed/expected ratio (o/e) 1.37, 90% interval 1.26 to 1.49. Synonymous variants: 190 observed, 138.72 expected, observed/expected ratio (o/e) 1.37, 90% interval 1.22 to 1.54.
Gene-disease validity (ClinGen):
ClinGen rates the evidence that APOLD1 causes each of these diseases.
inherited blood coagulation disorder (autosomal dominant): Limited. Hemorrhagic and thrombotic disorders that occur as a consequence of inherited abnormalities in blood coagulation.
Homologues: Orthologues: chimpanzee APOLD1 (99% identical), macaque APOLD1 (98% identical), pig APOLD1 (89% identical), mouse Apold1 (88% identical), rat Apold1 (88% identical), rabbit APOLD1 (86% identical), dog APOLD1 (85% identical), guinea pig APOLD1 (79% identical), tropical clawed frog apold1 (43% identical), zebrafish apol1 (25% identical), zebrafish si:cabz01007807.1 (25% identical), zebrafish apold1b (23% identical), and 3 more. Paralogues in human: APOL6 (23% identical), APOL3 (21% identical), APOL4 (20% identical), APOL2 (19% identical), APOL1 (19% identical), APOL5 (16% identical).
Diseases named in the same sentence as APOLD1 in open-access papers:
APOLD1 is named in the same sentence as 29 diseases in open-access papers, as found by Europe PMC text mining. Sharing a sentence is not in itself a finding about the gene and the disease. The quoted sentences say what the papers report.
high blood pressure (2 papers, 2020 to 2024). "For instance, APOLD1, which was significantly (P < 0.05) associated with cardiovascular (e.g., high blood pressure), respiratory (e.g., asthma) and hematological (e.g., hemoglobin) traits, showed significant expression changes in the heart, lung and kidney." (PMID 38730227, 2024).
ischaemic stroke (2 papers, 2021 to 2023). "Thus, Apold1−/− mice show impaired angiogenesis in the ischemic stroke border zone during the three-week recovery period." (PMID 36933174, 2023). "Also worth mentioning, PHB confer strong protection against neuronal injury in models of cerebral ischaemia, evoking promotion of autophagy, which would also contribute to explain the protection afforded by the APOL‐related APOLd1 against ischaemic stroke, assuming that PHB act together with APOLd1." (PMID 32530132, 2021).
ischemia (2 papers, 2023 to 2026). A hypoperfusion of the BLOOD through an organ or tissue caused by a PATHOLOGIC CONSTRICTION or obstruction of its BLOOD VESSELS, or an absence of BLOOD CIRCULATION. "Consistent with our observations in stroke, EdU labeling of proliferating mECs at 7 days following induction of ischemia revealed that Apold1-deficient mECs were unable to proliferate in response to ischemia." (PMID 36933174, 2023). "We report that Apold1 is dispensable for developmental angiogenesis, but it is necessary for functional revascularization during recovery from ischemia in the central nervous system and in the periphery." (PMID 36933174, 2023). "Additionally, we observed robust upregulation of APOLD1, an early‐response endothelial protein induced by ischemia." (PMID 41486637, 2026). "Taken together, we here show that Apold1 is dispensable for developmental angiogenesis, but that it controls ischemia-induced revascularization of the brain (stroke) and muscle (femoral artery ligation) and regulates pathological tumor angiogenesis, probably largely by controlling EC proliferation." (PMID 36933174, 2023). "In this study, we report that the vascular gene Apold1 is dispensable for developmental angiogenesis but that it crucially contributes to ischemia-induced revascularization of the brain (stroke) and muscle (femoral artery ligation) as well as tumor angiogenesis by controlling EC proliferation." (PMID 36933174, 2023). "Isolation of muscle endothelial cells (mECs) from the ligated hindlimb 3 days after induction of ischemia revealed a nearly 20-fold increase in Apold1 mRNA content when compared to the non-ligated contralateral side (right)." (PMID 36933174, 2023).
Stroke (2 papers, 2023 to 2026). Sudden impairment of blood flow to a part of the brain due to occlusion or rupture of an artery to the brain. "Apold1-deficient pups showed reduced angiogenesis after stroke and had impaired long-term functional recovery." (PMID 36933174, 2023). "However, in adult mice, where Apold1 expression is much lower, acute stroke caused similar size lesions and comparable functional impairment (24–72 h after stroke) in Apold1−/− mice and wild-type controls." (PMID 36933174, 2023). "Because revascularization of the ischemic area is crucial for functional recovery in preclinical mouse models and patients after stroke, we speculate that loss of Apold1 might impair functional recovery in stroke." (PMID 36933174, 2023). "Future investigations should evaluate the function of APOLD1 in nEB‐NSCs induced vascular regeneration, potentially revealing a novel mechanism for post‐stroke recovery." (PMID 41486637, 2026). "We also found higher Apold1 levels in muscle ECs during hindlimb ischemia and in the brain upon stroke." (PMID 36933174, 2023). "As expected, Apold1 expression increased in the microdissected peri-infarct tissue 2 days after stroke and returned to baseline levels within a week (right)." (PMID 36933174, 2023). "Labeling of proliferating cells one week after stroke using 5-ethynyl-2’-deoxyuridine (EdU) injections combined with immunofluorescent labeling of PECAM1+ ECs showed that Apold1−/− ECs within the ischemic border zone proliferate less." (PMID 36933174, 2023). "To subsequently study the role of Apold1 during angiogenesis in pathological settings, we turned to a mouse model of stroke." (PMID 36933174, 2023). "In a mouse model of neonatal stroke, Apold1−/− pups showed reduced angiogenesis after stroke and impaired long-term functional recovery." (PMID 36933174, 2023). "However, when exposed to ischemic conditions following photothrombotic stroke as well as femoral artery ligation, Apold1−/− mice display dramatic impairments in recovery and revascularization." (PMID 36933174, 2023). "Importantly, the role of Apold1 in recovery from stroke, including angiogenesis and revascularization, was not assessed." (PMID 36933174, 2023).
bleeding disorder (1 paper, 2023). "In this respect, a mutation in Apold1 was recently described in a family of patients with a novel inherited bleeding disorder, yet Apold1 knockout mice (Apold1−/−) present with higher platelet reactivity and a prothrombotic phenotype." (PMID 36933174, 2023).
colorectal cancer (1 paper, 2023). A primary or metastatic malignant neoplasm that affects the colon or rectum. "In contrast, another study found that Apold1 DNA is hypomethylated and its expression strongly increased in two independent cohorts of patients with colorectal cancer." (PMID 36933174, 2023).
lupus nephritis (1 paper, 2024). Glomerulonephritis in the context of systemic lupus erythematosus. "Moreover, variants in APOLD1 are potentially associated with an increased risk of advanced lupus nephritis." (PMID 39624492, 2024).
lymphoma (1 paper, 2010). A malignant (clonal) proliferation of B- lymphocytes or T- lymphocytes which involves the lymph nodes, bone marrow and/or extranodal sites. "In a preliminary screening of various primary tumours, the expression of APOLD1 was downregulated in tumours of not only the testis but also those of the ovary, lymphoma, kidney, bladder and cervix." (PMID 20051947, 2010).
melanoma (1 paper, 2023). A malignant, usually aggressive tumor composed of atypical, neoplastic melanocytes. "To functionally test the role of Apold1 in tumorigenesis, we implanted syngeneic B-16-F10 melanoma cells in WT and Apold1−/− mice and followed tumor growth over time." (PMID 36933174, 2023). "In a mouse model of melanoma (B16-F10), we found that subcutaneous tumor growth was reduced in Apold1−/− mice." (PMID 36933174, 2023). "We also find that human tumor endothelial cells express strikingly higher levels of Apold1 and that Apold1 deletion in mice stunts the growth of subcutaneous B16 melanoma tumors, which have smaller and poorly perfused vessels." (PMID 36933174, 2023).
prostate carcinoma (1 paper, 2024). A carcinoma that arises from epithelial cells of the prostate gland. "That is, the variant in enhancer ‘chr12:12713282–12727320’ would intervene LY-294002 sensitivity in prostate cancer patients through altering the regulation of LY-294002 perturbed gene: APOLD1." (PMID 38816426, 2024).
pulmonary hypertension (1 paper, 2024). Increased pressure within the pulmonary circulation due to lung or heart disorder. "For instance, APOLD1 and KCNA5, which are associated with pulmonary hypertension, showed similar expression patterns to BMPR2 in lung, artery and heart." (PMID 38730227, 2024).
schizophrenia (1 paper, 2017). A major psychotic disorder characterized by abnormalities in the perception or expression of reality. "The paralogous genes of GBP1, MT2A and APOL1, including GBP2, MT1G, MT1E, MT1F, MT1L and APOLD1, were also upregulated in the schizophrenia cases." (PMID 28809853, 2017).
cancer (4 papers, 2010 to 2023). A tumor composed of atypical neoplastic, often pleomorphic cells that invade other tissues. "Vascular heterogeneity, determined by tumor origin and type, is a hallmark feature of cancer and might explain these differences in Apold1 regulation." (PMID 36933174, 2023). "Although little is known about the possible role of Apold1 in cancer, two studies have reported dysregulation of Apold1 expression through DNA methylation." (PMID 36933174, 2023). "Therefore, we used single-cell datasets to evaluate Apold1 expression in human cancer." (PMID 36933174, 2023). "Before this study, RGAG1and APOLD1 were not known to be epigenetically silenced in cancers." (PMID 20051947, 2010).
tumor (3 papers, 2010 to 2023). "We found that loss of Apold1 reduced the percentage of proliferating (Edu+) ECs leading to a lower fraction of ECs inside the tumor." (PMID 36933174, 2023). "Altogether, these results demonstrate a critical role for Apold1 in angiogenesis and revascularization after hypoxic injury in the CNS and in the periphery, as well as during tumor growth." (PMID 36933174, 2023). "We found that Apold1 expression is restricted to ECs and is higher in tumor ECs when compared to normal ECs, confirming its relevance in humans." (PMID 36933174, 2023). "Strikingly, we found that within ECs, Apold1 expression was enriched in tumor ECs (tECs) compared to pulmonary ECs (pECs)." (PMID 36933174, 2023). "While WT mice showed exponential tumor growth, tumor growth was retarded in Apold1−/− mice leading to lower tumor volume and tumor weight at end stage." (PMID 36933174, 2023). "Combined PECAM1 and ACTA2 staining showed similar vessel (PECAM1+) area with similar coverage by pericytes (ACTA2+) in the tumor tissue of both WT and Apold1−/− mice." (PMID 36933174, 2023). "We also find that human tumor ECs express strikingly higher levels of Apold1 and that Apold1 deletion in mice reduces tumor growth by limiting EC proliferation." (PMID 36933174, 2023). "In this study, we identified three immune-related genes, VEGFC, VCAN, and TNFSF, overexpressed in tumor tissues of high-risk patients and PDXY and APOLD1 upregulated in the low-risk group." (PMID 35382776, 2022). "RNA samples of each tumour type and the corresponding normal adjacent tissue were collected from a single individual; therefore, the role of APOLD1 as a tumour-suppressor gene awaits further confirmation with examples of more tumour specimens." (PMID 20051947, 2010). "However, closer investigation of the tumor vasculature showed that Apold1−/− mice had more vessels, but these vessels had a much smaller lumen, resulting in a dramatic reduction in lumen area per vessel in Apold1−/− mice." (PMID 36933174, 2023). "Because of the profound role of Apold1 in regulating angiogenesis in pathological settings, we next asked whether Apold1 controls tumor angiogenesis." (PMID 36933174, 2023). "While these data require confirmation in other, more chronic tumor models, they suggest that inhibiting Apold1 could prevent uncontrolled endothelial proliferation in pathological settings." (PMID 36933174, 2023).
vascular disorder (1 paper, 2026). A general term used to describe any disease affecting blood vessels]. "APOLD1 deficiency impairs PI3K/Akt signaling and enhances platelet reactivity, further emphasizing its function in vascular integrity as well as its therapeutic targeting in vascular disorders." (PMID 41486637, 2026).
APOLD1 also shares sentences with these, for which no sentence is quoted: embryonal carcinoma (2 papers); seminoma (2); asthma (1); Cerebral ischemia (1); deep venous thrombosis (1); glioma (1); Hypertension (1); reproductive system diseases (1); testicular embryonal carcinoma (1); testicular germ cell tumor (1); testicular tumor (1); Thromboembolism (1); venous thromboembolism (1); yolk-sac tumour (1).